RN7SL69P (RNA, 7SL, cytoplasmic 69, pseudogene)
Gene: Miscellaneous RNA gene on chromosome 12 (6,095,699 to 6,095,970, reverse strand). Ensembl gene ENSG00000240533.
Homologues: Orthologues: chimpanzee Metazoa_SRP (98% identical), macaque Metazoa_SRP (79% identical). Paralogues in human: RN7SL2 (83% identical), RN7SL1 (83% identical), RN7SL3 (82% identical), RN7SL664P (81% identical), RN7SL709P (80% identical), RN7SL478P (79% identical), RN7SL566P (79% identical), RN7SL679P (79% identical), RN7SL431P (79% identical), RN7SL625P (79% identical), RN7SL675P (79% identical), Metazoa_SRP (79% identical), and 702 more.